RCC1L (RCC1 like)
Description:
Guanine nucleotide exchange factor (GEF) for mitochondrial dynamin-related GTPase OPA1. Activates OPA1, by exchanging bound GDP for free GTP, and drives OPA1 and MFN1-dependent mitochondrial fusion. Plays an essential role in mitochondrial ribosome biogenesis. As a component of a functional protein-RNA module, consisting of RCC1L, NGRN, RPUSD3, RPUSD4, TRUB2, FASTKD2 and 16S mitochondrial ribosomal RNA (16S mt-rRNA), controls 16S mt-rRNA abundance and is required for intra-mitochondrial translation of core subunits of the oxidative phosphorylation system. [Isoform 1]: Plays an essential role in mitochondrial ribosome biogenesis via its association with GTPases that play a role in the assembly of the large ribosome subunit. [Isoform 2]: Plays an essential role in mitochondrial ribosome biogenesis via its association with GTPases that play a role in the assembly of the small ribosome subunit.
Synonyms: WBSCR16
Tractability: PROTAC: ubiquitination databases record sites on it.
Gene: Protein-coding gene on chromosome 7 (75,027,122 to 75,074,228, reverse strand). Ensembl gene ENSG00000274523.
Subcellular location: Mitochondrion membrane; Mitochondrion inner membrane (Isoform 1); Mitochondrion inner membrane (Isoform 2); Mitochondrion inner membrane (Isoform 3)
Pathways (Reactome):
Metabolism of RNA: Mitochondrial mRNA modification; rRNA modification in the mitochondrion
Gene Ontology:
Molecular function: guanyl-nucleotide exchange factor activity; protein binding; RNA binding; rRNA binding
Biological process: mitochondrial fusion; mitochondrial large ribosomal subunit assembly; mitochondrial ribosome assembly
Cellular component: mitochondrial inner membrane; mitochondrial matrix; mitochondrial membrane; mitochondrion
Genetic constraint (gnomAD): Loss-of-function variants: 45 observed, 56.34 expected, observed/expected ratio (o/e) 0.8, 90% interval 0.63 to 1.02. The upper end of that interval is the gene's LOEUF score, 1.02, which puts it in group 4 of 6, group 1 being the genes least tolerant of losing a copy. Missense variants: 606 observed, 574.35 expected, observed/expected ratio (o/e) 1.06, 90% interval 0.99 to 1.13. Synonymous variants: 270 observed, 235.8 expected, observed/expected ratio (o/e) 1.14, 90% interval 1.04 to 1.27.
Homologues: Orthologues: chimpanzee RCC1L (99% identical), macaque RCC1L (97% identical), pig RCC1L (93% identical), chimpanzee RCC1L (91% identical), mouse Rcc1l (90% identical), rat Rcc1l (85% identical), guinea pig RCC1L (85% identical), rabbit RCC1L (81% identical), tropical clawed frog rcc1l (68% identical), zebrafish rcc1l (65% identical), dog RCC1L (58% identical), Drosophila melanogaster CG3862 (39% identical), and 2 more. Paralogues in human: HERC1 (27% identical), RCBTB1 (23% identical), RCC1 (22% identical), RCBTB2 (22% identical), RCC2 (21% identical), ALS2 (20% identical), RPGR (20% identical), SERGEF (18% identical), RCCD1 (17% identical).
Diseases named in the same sentence as RCC1L in open-access papers:
RCC1L is named in the same sentence as 1 disease in open-access papers, as found by Europe PMC text mining. Sharing a sentence is not in itself a finding about the gene and the disease.
RCC1L shares sentences with these, for which no sentence is quoted: adrenal cortical carcinoma (1 paper).